CAPRIN1 (cell cycle associated protein 1)
Diseases named in the same sentence as CAPRIN1 in open-access papers (continued):
Sharing a sentence is not in itself a finding about the gene and the disease.
cancer (continued). "Here, we have successfully identified CAPRIN-1 as a novel truly cancer-specific target, universally expressed on membranes of various cancer cells including cancer stem cells." (PMID 37082579, 2023). "Our findings underline novel mechanisms of Caprin-1-induced autophagy activation and immunomodulation in PDAC progression, which provide evidence of targeting Caprin-1 on cancer treatment." (PMID 38082307, 2023). "On the other hand, tissue staining data from Protein Atlas showed the expression of CAPRIN-1 in both normal tissues and cancer tissues with a high score of almost 100%." (PMID 37082579, 2023). "When the mRNA expression of CAPRIN-1 was compared between cancer tissues (The Cancer Genome Atlas data) and normal tissues (GTex data) at the GEPIA site, the expression tended to be high in cancer tissues." (PMID 37082579, 2023). "Further investigations to gain insights into the mechanisms of how CAPRIN-1 is recruited to the cancer cell membrane and its potential molecular interactions with other surface proteins are warranted and will be the subject of future basic research." (PMID 37082579, 2023). "While the clinical outcomes and pathophysiology of ESCA and OA seems to be different, Caprin-1 expression displayed different OS patterns in these cancers." (PMID 36855123, 2023). "Caprin-1 has been reported to be a regulator of mRNA translation and is abnormally expressed in various cancers." (PMID 36732659, 2023). "Recombinant CAPRIN-1 protein inhibited the binding of anti-CAPRIN-1 antibodies to the surface of cancer cell membranes." (PMID 37082579, 2023). "To further confirm that CAPRIN-1 is indeed expressed on cancer cell membranes, we separated BT-474 cells into cytosolic and membrane fractions for evaluation by Western blotting." (PMID 37082579, 2023). "Consistently, cancer cells with particularly high CAPRIN-1 surface expression exhibited enhanced in vitro colony-forming activity and in vivo tumorigenicity." (PMID 37082579, 2023). "Molecular characterization of CAPRIN1 in NPC will be helpful for clarifying the roles of a variety of RNA-binding proteins in cancer." (PMID 36515758, 2022). "In the absence of glutamine, an increase in GIRGL LncRNA levels in the cell forms a complex between GLS1 mRNA and CAPRIN1, which induces SGs and inhibits GLS1 mRNA translation by increasing the LLPS process in CAPRIN1, allowing the cancer cell to survive." (PMID 34604242, 2021). "miR-16 also targets Caprin-1 (cytoplasmic activation/proliferation-associated protein-1) and Cyclin E in MCF-7 and HeLa cancer cell lines." (PMID 31963852, 2020). "Caprin1 overexpression protected cancer cells from AS, H2O2 or DOC-induced cell death as measured by propidium iodide staining, while Caprin1 knockout sensitized cancer cells to stress-induced cell death." (PMID 31771591, 2019). "Previously, we reported that tylophorine-based compounds exert anti-cancer activity predominantly by targeting the RNP complex containing caprin-1 protein/c-Myc mRNA in carcinoma cells." (PMID 28642467, 2017). "Caprin1 is found to be upregulated in various types of cancers 177,178." (PMID 40521202, 2025). "In addition, we found that cancer stem cells derived from patients with pancreatic cancer also strongly expressed CAPRIN-1 on their cell surface and exhibited enhanced in vitro colony-forming activity and in vivo tumorigenicity." (PMID 40557916, 2025). "Positive ratio of CAPRIN-1 on cell membrane was remarkably high in various cancer tissues." (PMID 37082579, 2023). "Indeed, the subsequently developed humanized and clinical-grade anti-CAPRIN-1 antibody TRK-950 efficiently eliminates various cancer cells and showed an excellent safety profile in primates." (PMID 37082579, 2023). "The extensive CD4+T cells determined poor clinical outcome in Caprin-1high patients, arguing that highly expressed Caprin-1 may assist cancer cells to escape from immune surveillance." (PMID 38082307, 2023).
cancer (continued). "Among them, we found that hsa-miR-199a-5p could target CAPRIN1, an RNA-binding protein generally overexpressed in various cancer types that acts as a modulator of cell proliferation, immune checkpoint proteins, and resistance to radiation and chemotherapy." (PMID 36979715, 2023). "Caprin-1 possesses RNA binding characteristics and affects cancer cells survival." (PMID 38082307, 2023). "In this process, we identified CAPRIN-1 as a novel candidate target for cancer treatment." (PMID 37082579, 2023). "Furthermore, the expression of CAPRIN-1 in cancer tissue and normal tissue arrays was analyzed via IHC using mAb-1." (PMID 37082579, 2023). "In addition, Caprin-1 recruits CD4+T cells and tumor associated macrophages (TAMs) infiltration in TME, indicating Caprin-1High cancer cells are likely to escape from immune surveillance and fail to respond to immunotherapy." (PMID 38082307, 2023). "We analyzed CAPRIN-1 expression on various types of cancer cells using mAb-1 for flow cytometry." (PMID 37082579, 2023). "Together, our data demonstrate that CAPRIN-1 is a novel and universal target for cancer therapies." (PMID 37082579, 2023). "Importantly, TRK-950 exhibited cytotoxicity and phagocytosis to CAPRIN-1+ cancer cells in a dose-dependent fashion." (PMID 37082579, 2023). "To further explore whether CAPRIN-1 is indeed expressed on cancer cell membranes, we next generated a large variety of mAbs binding to CAPRIN-1 protein from rabbits, mice, and chicken." (PMID 37082579, 2023). "Importantly, CAPRIN-1 is also very highly expressed on the membrane surface of highly tumorigenic cancer stem cells." (PMID 37082579, 2023). "In addition, we revealed that cancer cells with particularly high CAPRIN-1 surface expression exhibited enhanced tumorigenicity." (PMID 37082579, 2023). "To further confirm whether antibodies that bound to the surface of cancer cell membranes specifically recognize CAPRIN-1, we conducted Western blot analysis with cell lysates and a single band was detected at approximately 120 kDa." (PMID 37082579, 2023). "Caprin-1 has been reported to be abnormally expressed in various cancers." (PMID 36732659, 2023). "Together, these data suggest that CAPRIN-1 could be an attractive and widely applicable therapeutic target for cancer, for example, antibody-based treatment approaches." (PMID 37082579, 2023). "Since CCND2 is an important cyclin protein in cancer cells, CAPRIN1 may promote cell proliferation by regulating the cell cycle through binding to CCND2 to induce its expression in NPC." (PMID 36515758, 2022). "Recent studies suggest that CAPRIN1 may have an oncogenic role in the development of a variety of types of cancer." (PMID 36515758, 2022). "However, we noticed that all SGs nucleators (TIA-1, TIAR, G3BP1, G3BP2, and CAPRIN-1) have an “enhancing” effect on cancer development properties, whereas USP10, a SGs inhibitor, has anti-cancer properties." (PMID 32882814, 2020). "We examined the interactions between cancer-associated mutants of SPOP and Caprin1 by co-IP assays." (PMID 31771591, 2019). "Caprin-1 is an RNA-binding protein that plays critical roles in human cancers." (PMID 30687106, 2018). "The impact of miR-193a-mediated interruption of the caprin-1/G3BP-1/c-MYC/Cyclin D2 complex could be a potential target for anti-cancer therapeutic applications." (PMID 28211508, 2017). "However, we did not observe the polysomal colocalization of G3BP1, c-Myc mRNA, and cyclins D1/D2 mRNA with caprin-1 in the DMSO-treated carcinoma cells by sedimentation fractionation." (PMID 25669982, 2015). "Moreover, the latest research has demonstrated that lncRNA CAPRIN1 can inhibit GLS1 translation by driving CAPRIN1-mediated phase segregation in glutamine deficiency, preventing excessive depletion of limited glutamine to maintain cancer survival." (PMID 38238756, 2024).
cancer (continued). "Therefore, it came as a great surprise when we detected CAPRIN-1 on the cell surface and later could indeed validate CAPRIN-1 as a cancer-specific cell surface antigen." (PMID 37082579, 2023). "In fact, caprin-1 may help drive tumorigenesis in several cancers." (PMID 34376192, 2021). "Moreover, the induction of cell cycle arrest at G1 by knockdown of caprin-1 suggests that, in addition to the caprin-1 and c-Myc mRNA-associated RNP complex, caprin-1 itself may have favorable potential as a novel anti-cancer drug target." (PMID 25669982, 2015). "Overall, we concluded that the use of Caprin1 and USP10-derived SIPs is an effective way to promote the efficacy of sorafenib treatment in cancer cells." (PMID 38731625, 2024). "Among the m6A regulators in the regulatory network, we found that CAPRIN1, a novel METTL3 co-factor, was positively correlated with cancer-specific m6A." (PMID 38970366, 2024). "TRK-950 maintained the specificity of the original antibody and consistently binds to both CAPRIN-1 protein and CAPRIN-1 on the surface of cancer cell membranes." (PMID 37082579, 2023). "Importantly, CAPRIN-1 could not be detected on the membrane surface of white blood cells isolated from healthy volunteers, normal human fibroblasts, and cancer-associated fibroblasts from patients with PDAC." (PMID 37082579, 2023). "We generated a therapeutic humanized anti-CAPRIN-1 antibody (TRK-950), which strongly and specifically binds to various cancer cells and shows antitumor effects via engagement of immune cells." (PMID 37082579, 2023). "Our data reveals that Caprin-1 induces the dephosphorylation of ULK1 and triggers autophagosome fusion that maintains cancer cells growth." (PMID 38082307, 2023). "Predicted genes targeted by dysregulated oncomiRs or tumor suppressor miRNAs were mainly involved in cell cycle regulators such as CAPRIN1, CDC42, PTEN, IGF1R, BRCA1 and CD28, thereby controlling cancer dormancy." (PMID 33374139, 2020). "We are the first to report that targeting an RNP complex (i.e., targeting the caprin-1 and c-Myc mRNA-containing RNP complex by tylophorine compounds) in carcinoma cells can efficiently elicit anti-cancer activity." (PMID 25669982, 2015). "This hypothesis was also confirmed by the association of caprin-1 with G3BP1, c-Myc mRNA, and cyclins D1/D2 in polysomal fractions only in tylophorine- but not vehicle-treated carcinoma cells, whereas the c-Myc mRNA and cyclins D1/D2 mRNA levels were elevated in tylophorine-treated carcinoma cells." (PMID 25669982, 2015). "Additionally, in the pan-cancer datasets (TCGA, TARGET, and GTEx), CAPRIN1 showed significant correlations with 60 immune checkpoints." (PMID 40819077, 2025). "Therefore, we selected these two cancer types, which showed the best response, to explore the correlation between TRK-950 efficacy and CAPRIN-1 expression, as well as the characterization of the immunologic events associated with the treatment of TRK-950." (PMID 40557916, 2025). "In addition, changes in CAPRIN1 expression and localisation have also been linked to cancer; in particular, the recent detection of CAPRIN1 on the cell membrane surface in many solid cancers, but not normal tissues, makes it an attractive novel target for cancer therapeutics." (PMID 40063661, 2025). "On the basis of our initial data using our newly generated anti-CAPRIN-1 antibodies, we reported the possibility that CAPRIN-1 is specifically expressed on cancer cell membranes and could be a target for antibody cancer treatment." (PMID 37082579, 2023). "Most of the generated antibodies, such as mAb-7, mAb-8, and mAb-9, bound to recombinant CAPRIN-1 protein but did not bind to the surface of cancer cell membranes." (PMID 37082579, 2023). "Lack of expression on nontransformed cells suggests that CAPRIN-1 represents a promising target for cancer immunotherapies with a large therapeutic window due to low risk for adverse reactions related to non-cancer targeting." (PMID 37082579, 2023).
cancer (continued). "The absence of Caprin-1 leads to cancer cell proliferation, migration, and invasion defects and immune cells proliferation." (PMID 36855123, 2023). "In conclusion, CAPRIN1 might drive NPC proliferation, regulate cell cycle and apoptosis, and affect tumor cell response to anti-cancer agents and X-ray irradiation." (PMID 36515758, 2022). "Thus, we conclude that the elevation of c-Jun levels by tylophorine functions in concert with the targeting of the caprin-1 and c-Myc mRNA-containing RNP complex to produce the anti-cancer activity of tylophorine compounds." (PMID 25669982, 2015). "We previously demonstrated that CAPRIN-1 is strongly expressed on the cell membrane surface in or on most solid cancers but not in or on normal tissues and that CAPRIN-1 is present in the cytoplasm in both cancer and normal tissues, which is consistent with previous reports." (PMID 40557916, 2025). "We further fused Caprin1 and USP10-derived peptides with a cell-penetrating peptide; the synthesized TAT-SIP-C1/2 and SIP-U1-Antp could effectively block sorafenib-induced SGs and improve the sensitivity of cancer cells to sorafenib-induced cell death." (PMID 38731625, 2024). "Indeed, we found that Tunicamycin increased surface CAPRIN-1 expression in cancer cells with virtually no CAPRIN-1 expression at baseline." (PMID 37082579, 2023). "We confirmed that CAPRIN-1 is present in the cytoplasm, which is consistent with previous reports, and simultaneously determined that a part of the total CAPRIN-1 is actually exposed on the cell membrane surface, a phenomenon that occurs exclusively in cancer cells." (PMID 37082579, 2023). "Moreover, commercially available anti-CAPRIN-1 antibodies, such as mAb-10 and pAb-2, also did not bind to the surface of cancer cell membranes." (PMID 37082579, 2023). "Depletion of caprin-1 by tylophorine increased cancer cell resistance and decreased the formation of tylophorine-targeted RNP; moreover, c-Myc and cyclins D1/D2 are downregulated by the retinoblastoma tumor suppressor protein pRb (retinoblastoma protein), leading to cancer cell cycle block." (PMID 37892993, 2023). "Notably, cancer cell surface expression of CAPRIN-1 was not affected by the EMT process, which is an important initial step of the metastatic process." (PMID 37082579, 2023). "While CAPRIN-1 is not expressed on the cell membrane surface of nontransformed cells, it is strongly and reproducibly expressed on the cell membrane surface of many cancer types." (PMID 37082579, 2023). "Ultimately, the blockade of c-Myc mRNA transport by the tylophorine-mediated sequester of the caprin-1, G3BP1, c-Myc mRNA, and cyclin D2 mRNA-containing RNP complex may contribute significantly to the anti-cancer effects elicited by tylophorine in conjunction with the accumulation of c-Jun." (PMID 25669982, 2015). "Knowing that cytoplasmic CAPRIN-1 migrates and accumulates in stress granules in response to stressful stimuli, we exposed cancer cells to the Endoplasmic Reticulum (ER) stress inducer Tunicamycin and evaluated whether the expression level of CAPRIN-1 on the cancer cell membranes changes." (PMID 37082579, 2023). "STK38 is implicated to suppress the transcription of ULK1, we then explored the expressions of STK38, ULK1 and p-ULK1 in the absence of Caprin-1 or/and STK38 cancer cells." (PMID 38082307, 2023).
tumor (29 papers, 2014 to 2025). "The experimental methods and correlation analysis of Caprin-1 with 18F-FDG PET parameters in ESCA were combined to explore mechanisms underlying the functions of Caprin-1 in tumor growth and glycolysis reprogramming." (PMID 36855123, 2023). "Caprin-1 has also been implicated in tumor-promoting inflammation, fibrosis and T cells recruitment." (PMID 38082307, 2023). "We found that higher levels of miR-193a in tumour cells cause cell cycle G1 arrest and cell proliferation repression through reduction of caprin-1 expression." (PMID 28211508, 2017). "Furthermore, the associations between Caprin-1 expression in tumors and patients’ clinical parameters were investigated using two independent datasets, both of which suggested that higher Caprin-1 expression was associated with larger tumor size and poor prognosis." (PMID 38082307, 2023). "Conversely, miR-497-5p inhibitor treatment resulted in a significant increase in tumor cell density and a decrease in necrotic areas, while sh-CAPRIN1 treatment led to a significant reduction in tumor cell density and an increase in necrotic areas." (PMID 40819077, 2025). "Cytoplasmic activation/proliferation-associated protein-1 (Caprin-1), whose expression is significantly elevated in both ESCA tumor tissues and cell lines, is associated with poor prognosis in ESCA patients." (PMID 40356985, 2025). "To further validate the effect of exo/si-LINC02544 on tumor growth in immune therapy-resistant TNBC xenograft models via the miR-497-5p/CAPRIN1 axis, we established immune therapy-resistant TNBC xenograft mice by injecting MDA-MB-231/PEM cells." (PMID 40819077, 2025). "In contrast, the miR-497-5p inhibitor treatment accelerated tumor growth and increased tumor size, while sh-CAPRIN1 treatment slowed tumor growth and reduced tumor size." (PMID 40819077, 2025). "By physically attaching to CAPRIN1 and G3BP1, circVAMP3 exhibited tumor suppressor qualities in HCC by causing CAPRIN1 to phase separate and promoting the production of stress granules, which prevented the translation of c-Myc." (PMID 38322286, 2023). "Further study indicated that overexpression of Caprin-1 promoted tumor growth in vivo and knockdown of Caprin-1 limited tumor progression." (PMID 38082307, 2023). "We found that knockdown of Caprin-1 slightly inhibited tumor growth, while the expression of LC3, as well as infiltrated numbers of CD4 and F4/80 positive cells were dramatically reduced." (PMID 38082307, 2023). "Taken together, our results reveal that Caprin-1 promotes tumor progression and can be a biomarker for evaluating PDAC patients' prognosis." (PMID 38082307, 2023). "These suggest that Caprin-1 potentiates immune surveillance and tumor progression by altering T cells and macrophage infiltration." (PMID 38082307, 2023). "In TLN, Caprin-1 suppressed activation of lymphocytes, T cell activation and anti-tumor cytokine and chemokine (IFNG, IL1B, IL21 and TNF) production." (PMID 38082307, 2023). "We found that overexpression of Caprin-1 expedited tumor cells proliferation, and knockdown of Caprin-1 attenuated the phenotype." (PMID 38082307, 2023). "Caprin-1 expression was significantly elevated in both ESCA tumor tissues and cell lines compared with that in normal adjacent tissues and fibroblasts." (PMID 36855123, 2023). "Herein, knockdown of caprin-1 in GC cells resulted in a significant blockage of malignant cell proliferation and tumor incidence, in line with circIPO7 overexpression." (PMID 36732659, 2023). "The mechanisms by which CAPRIN1 regulates tumor cell progression and the therapeutic response through stress pathways were not fully elucidated in our study." (PMID 36515758, 2022). "Among the interactors, caprin-1 is involved in tumor proliferation, migration,and invasion as well as prognosis in HCC." (PMID 34376192, 2021).